GTPBP2 (GTP binding protein 2)
Description:
Involved in the rescue of ribosome stalling due to the presence of non-functional tRNA (By similarity). Has very low GTP-binding activity.
Synonyms: JABELS
Tractability: Antibody: its Gene Ontology location is reachable by antibodies, with high confidence. PROTAC: ubiquitination databases record sites on it; its protein half-life has been measured.
Gene: Protein-coding gene on chromosome 6 (43,605,316 to 43,629,264, reverse strand). Ensembl gene ENSG00000172432.
Subcellular location (Human Protein Atlas): Vesicles
Pathways (Reactome):
Hemostasis: Platelet degranulation
Gene Ontology:
Molecular function: alpha-aminoacyl-tRNA binding; GTP binding; identical protein binding; protein binding; translation elongation factor activity; GTPase activity
Biological process: translational elongation
Cellular component: extracellular region; platelet alpha granule lumen
Genetic constraint (gnomAD): Loss-of-function variants: 31 observed, 60.42 expected, observed/expected ratio (o/e) 0.51, 90% interval 0.38 to 0.69. The upper end of that interval is the gene's LOEUF score, 0.69, which puts it in group 2 of 6, group 1 being the genes least tolerant of losing a copy. Missense variants: 483 observed, 799.15 expected, observed/expected ratio (o/e) 0.6, 90% interval 0.56 to 0.65. Synonymous variants: 304 observed, 327.7 expected, observed/expected ratio (o/e) 0.93, 90% interval 0.84 to 1.02.
Gene-disease validity (ClinGen):
ClinGen rates the evidence that GTPBP2 causes each of these diseases.
Jaberi-Elahi syndrome (autosomal recessive): Definitive.
Homologues: Orthologues: chimpanzee GTPBP2 (100% identical), dog GTPBP2 (99% identical), guinea pig GTPBP2 (99% identical), pig GTPBP2 (99% identical), mouse Gtpbp2 (99% identical), rat Gtpbp2 (99% identical), rabbit GTPBP2 (96% identical), macaque GTPBP2 (91% identical), zebrafish gtpbp2b (79% identical), tropical clawed frog gtpbp2 (72% identical), Drosophila melanogaster CG2017 (47% identical), Caenorhabditis elegans slfl-5 (41% identical). Paralogues in human: GTPBP1 (46% identical), EEF1A1 (18% identical), EEF1A2 (18% identical), GSPT1 (17% identical), GSPT2 (17% identical), EIF5B (15% identical), TUFM (14% identical), HBS1L (14% identical), MTIF2 (14% identical), EFL1 (13% identical), GFM2 (12% identical), GFM1 (12% identical), and 6 more.
Diseases named in the same sentence as GTPBP2 in open-access papers:
GTPBP2 is named in the same sentence as 22 diseases in open-access papers, as found by Europe PMC text mining. Sharing a sentence is not in itself a finding about the gene and the disease. The quoted sentences say what the papers report.
Ataxia (5 papers, 2020 to 2024). Ataxia refers to impaired coordination of voluntary muscle movement. "In mice, homozygous loss of GTPBP2 in combination with a second variant in a brain-specific arginine tRNA gene leads to a severe neurological disorder with severe motor deficits and progressive ataxia." (PMID 38118446, 2024). "Similarly, mutation of GTPBP2, a GTPase that mediates the splitting of stalled ribosomes upstream of RQC22, causes Jaberi–Elahi syndrome, an early onset neurodegenerative disease characterized by dystonia, motor and sensory neuropathy, ataxia, and cognitive dysfunction." (PMID 32934225, 2020).
intellectual disabilities (5 papers, 2016 to 2025). "The essential role of Gtpbp2 in neural homeostasis was further revealed by the fact that mutations in Gtpbp2 in humans cause neurodegeneration and intellectual disabilities." (PMID 36551964, 2022). "GTPBP2 allele-inactivating variants are associated with familial neurodevelopmental disorders and intellectual disabilities." (PMID 34093790, 2021). "The essential role of Gtpbp2 in neuronal homeostasis was further revealed by the identification of mutations in Gtpbp2 causing neurological defects and intellectual disabilities in humans." (PMID 33186095, 2020). "Recently, a mutation in the GTPBP2 gene was suggested to underlie cerebellar and retinal degeneration and intellectual disability in humans, supporting an essential role of GTPBP2 in neuronal homeostasis." (PMID 27085088, 2016).
retinal degeneration (3 papers, 2016 to 2025). Degeneration of the retina. "Alternatively, the group of Ackerman has shown that activation of Gcn2 plays a protective role in animal models of cerebellar and retinal degeneration caused by dual mutations in the ribosome rescue factor GTPBP2 and central nervous system (CNS)–specific tRNAArg." (PMID 40106564, 2025).
lymph node metastasis (2 papers, 2021 to 2022). "The high expression of GTPBP2 was positively correlated with the late stage of TNM stage (P = 0.005 <0.05), and was also positively correlated with lymph node metastasis (P = 0.014 <0.05), not related to age, gender, histological type and degree of differentiation." (PMID 34093790, 2021).
non-small cell lung carcinoma (2 papers, 2021 to 2023). A group of at least three distinct histological types of lung cancer, including non-small cell squamous cell carcinoma, adenocarcinoma, and large cell carcinoma. "Overexpression of EREG, GTPBP2, and DRG2 was linked to tumor growth in non-small cell lung cancer." (PMID 36809921, 2023). "GTPBP2 may be a potential target for the treatment of non-small cell lung cancer and provide new ideas for the treatment of non-small cell lung cancer." (PMID 34093790, 2021). "Therefore, we speculate that GTPBP2 may be a tumor suppressor gene for non-small cell lung cancer and participate in the development of non-small cell lung cancer." (PMID 34093790, 2021).
epilepsy (1 paper, 2024). A brain disorder characterized by episodes of abnormally increased neuronal discharge resulting in transient episodes of sensory or motor neurological dysfunction, or psychic dysfunction. "The clinical syndrome associated with bi-allelic GTPBP1 or GTPBP2 variants can be defined as a complex syndromic neurodevelopmental disorder associated with severe neurodegeneration, epilepsy, choreiform movement disorder, and ectodermal abnormalities, with pathognomonic craniofacial features." (PMID 38118446, 2024).
Jaberi-Elahi syndrome (1 paper, 2024). "The abnormal brain iron accumulation in the basal ganglia was also observed in other disorders, such as Kufor-Rakeb syndrome (KRS), Aceruloplasminemia (ACEP), Spastic paraplegia 35 (SPG35), and Jaberi-Elahi syndrome (JABELS), which were caused by mutated ATP13A2, CP, FA2H, GTPBP2, respectively." (PMID 38765101, 2024).
lung carcinoma (1 paper, 2021). "We found that the expression of GTPBP2 protein in fresh lung cancer tissues was different from that in normal tissues, and the expression level in fresh lung cancer tissues was higher than that in normal tissues." (PMID 34093790, 2021). "At present, the relationship between the expression of GTPBP2 gene and tumors has not been reported in domestic and foreign literatures, and the expression in human lung cancer has not been studied." (PMID 34093790, 2021).
microcephaly (1 paper, 2024). A congenital or acquired developmental disorder in which the circumference of the head is smaller than normal for the person's age and sex. "Individuals with bi-allelic GTPBP1 or GTPBP2 variants presented with microcephaly, profound neurodevelopmental impairment, pathognomonic craniofacial features, and ectodermal defects." (PMID 38118446, 2024).
Sepsis (1 paper, 2023). Sepsis is defined as life-threatening organ dysfunction caused by a dysregulated host response to infection. "Our study revealed that sepsis patients with high GTPBP2 expression had increased platelet activation, aggregation, and thrombosis, as well as higher levels of intracytoplasmic calcium ions in platelets." (PMID 38054005, 2023). "In our study, we constructed a machine learning model using five genes, including GTPBP2, ALDOA, PRKAR2A, KIF2C, and NHLRC2, to identify sepsis patients with a poor prognosis." (PMID 38054005, 2023). "In our investigation, we identified GTPBP2, ALDOA, PRKAR2A, NHLRC2, and KIF2C as genes related to sepsis death using three distinct techniques." (PMID 38054005, 2023).
cancer (4 papers, 2016 to 2024). A tumor composed of atypical neoplastic, often pleomorphic cells that invade other tissues. "A wide variety of cancer-causing Wnt pathway mutations require low Axin levels, so development of Gtpbp2 inhibitors may provide a new therapeutic strategy to elevate Axin and suppress aberrant β-catenin signaling in cancer and other Wnt-related diseases." (PMID 27484226, 2016). "The expression of GTPBP2 protein was also confirmed by immunohistochemistry in 112 cancer tissues and 65 adjacent normal lung tissues." (PMID 34093790, 2021). "First, Western blot and quantitative real-time PCR were used to analyze the expression differences of 12 cases of GTPBP2 in human NSCLC fresh cancer tissues and adjacent tissues." (PMID 34093790, 2021). "GTPBP2 had a stronger staining depth in cancer tissues than in adjacent tissues." (PMID 34093790, 2021). "Similarly, GTPBP2 is also known as a positive regulator of the Wnt signaling pathway, which is involved in tumorigenesis of a wide variety of cancers including CRC." (PMID 30952955, 2019). "However, GTPBP2 ablation or overexpression could not affect the expression of NANOG and other stemness markers in CD133−CD44− and CD133−CD44+ cells, suggesting that GTPBP2 no longer regulates stemness in non-CCSC cancer cells probably due to altered intracellular microenvironment." (PMID 38468952, 2024).
tumor (3 papers, 2021 to 2024). "We found fewer CD133+CD44+ cells (17.2%) in Gtpbp2−/− CCSC-derived tumor cells in comparison to Gtpbp2+/+ CCSC-derived tumor cells (22.6%), suggesting weaker self-renewal of Gtpbp2−/− CCSCs." (PMID 38468952, 2024). "No significant tumor cell invasion into adjacent tissues was seen in either Gtpbp2+/+ CCSC-derived tumors or Gtpbp2−/− CCSC-derived tumors." (PMID 38468952, 2024). "The relative mRNA level of GTPBP2 in the CRC tissue negatively correlated with mouse body weight and positively correlated with mean tumor volume but did not correlate with either tumor number or colon length, suggesting that GTPBP2 might enhance CRC growth." (PMID 38468952, 2024).
infection (1 paper, 2024). The state of being infected such as from the introduction of a foreign agent such as serum, vaccine, antigenic substance or organism. "After infection with the Cas9/sgRNA lentivirus, Gtpbp2−/− CD133+CD44− cells and Gtpbp2+/+ CD133+CD44− cells expressed comparable Ki67, proliferated at the same rate, and showed equivalent viability after 5-FU treatment." (PMID 38468952, 2024).
neurodevelopmental disorder (1 paper, 2024). A behavioral and cognitive disorder with onset during the developmental period that involves impaired or aberrant development of intellectual, motor, or social functions. "Pathogenic variants in GTPBP2 were recently shown to be an ultra-rare cause of neurodegenerative or neurodevelopmental disorders (NDDs)." (PMID 38118446, 2024). "We report molecular, clinical, and cellular findings in 20 affected individuals from 16 families affected with severe neurodevelopmental disorders and bi-allelic variants in GTPBP1 or GTPBP2." (PMID 38118446, 2024). "Rare genetic variants in GTPBP2 have been reported in recent years as a very rare cause of neurodegeneration with brain iron accumulation (NBIA) and/or severe neurodevelopmental disorders in a small group of consanguineous families from Iran, Northern Africa, and the Middle East." (PMID 38118446, 2024).
GTPBP2 also shares sentences with these, for which no sentence is quoted: colorectal cancer (1 paper); Dystonia (1); kidney cancer (1); Kufor-Rakeb syndrome (1); neurodegenerative disease (1); neurological disorder (1); renal carcinoma (1); Sensory neuropathy (1).